ADH1C (alcohol dehydrogenase 1C (class I), gamma polypeptide)
Description:
Alcohol dehydrogenase. Exhibits high activity for ethanol oxidation and plays a major role in ethanol catabolism.
Synonyms: ADH3
Tractability: Small molecule: an approved drug acts on it; a structure with a bound ligand is known; it has a high-quality binding pocket; it belongs to a druggable protein family. Antibody: its Gene Ontology location is reachable by antibodies, with high confidence. PROTAC: a small molecule that binds it is known.
Target class: Enzyme; Oxidoreductase
Safety:
Unwanted effects reported when the protein is acted on. In parentheses: how it was acted on, where the effect was seen, and who reports it.
alcoholism (source: ClinPGx)
Gene: Protein-coding gene on chromosome 4 (99,336,093 to 99,353,887, reverse strand). Ensembl gene ENSG00000248144.
Subcellular location: Cytoplasm
Subcellular location (Human Protein Atlas): Cytosol; Plasma membrane; Basal body; Nucleoplasm; Primary cilium; Primary cilium transition zone
Pathways (Reactome):
Metabolism: Ethanol oxidation
Signal Transduction: RA biosynthesis pathway
Gene Ontology:
Molecular function: alcohol dehydrogenase (NAD+) activity; ethanol dehydrogenase (NAD+) activity; protein binding; all-trans-retinol dehydrogenase (NAD+) activity; zinc ion binding; oxidoreductase activity
Biological process: retinoic acid metabolic process; retinol metabolic process
Cellular component: cytosol; cytoplasm
Genetic constraint (gnomAD): Loss-of-function variants: 26 observed, 36.4 expected, observed/expected ratio (o/e) 0.71, 90% interval 0.52 to 0.99. The upper end of that interval is the gene's LOEUF score, 0.99, which puts it in group 4 of 6, group 1 being the genes least tolerant of losing a copy. Missense variants: 412 observed, 480.41 expected, observed/expected ratio (o/e) 0.86, 90% interval 0.79 to 0.93. Synonymous variants: 170 observed, 171.45 expected, observed/expected ratio (o/e) 0.99, 90% interval 0.87 to 1.13.
Homologues: Orthologues: pig ADH1C (86% identical), mouse Adh1 (85% identical), rat Adh1c (82% identical), zebrafish adh5l (57% identical), zebrafish zgc:77938 (57% identical), zebrafish adh8a (55% identical), zebrafish adh8b (51% identical), Caenorhabditis elegans D2063.1 (21% identical), Caenorhabditis elegans adh-1 (20% identical), Caenorhabditis elegans sodh-2 (19% identical), Caenorhabditis elegans ZK829.7 (18% identical), Drosophila melanogaster Drat (14% identical). Paralogues in human: ADH1B (94% identical), ADH1A (93% identical), ADH7 (69% identical), ADH6 (63% identical), ADH5 (62% identical), ADH4 (60% identical), SORD (21% identical), CRYZ (21% identical), RTN4IP1 (21% identical), TP53I3 (21% identical), VAT1 (21% identical), MECR (20% identical), and 5 more.
Diseases named in the same sentence as ADH1C in open-access papers:
ADH1C is named in the same sentence as 73 diseases in open-access papers, as found by Europe PMC text mining. Sharing a sentence is not in itself a finding about the gene and the disease. The quoted sentences say what the papers report.
alcohol dependence (19 papers, 2007 to 2024). Physical and psychological dependence on alcohol. "Noteworthy variants also associated with alcohol dependence and consumption found to be enriched in the cohort included the risk alleles rs1614972 and rs698 in ADH1C, along with rs3762894 and rs671 in ADH4 and ALDH2, respectively." (PMID 38785976, 2024). "From GWAS (genome-wide association) of alcohol dependence in African- American, ADH1C rs2241894 (p.Thr151 =) is a risk loci mapped to alcohol-metabolizing enzyme genes." (PMID 33551739, 2021). "Previous studies showed that the genetic variations in ADH genes were related to alcohol consumption; however, this was more evident for the ADH2 gene, whereas the ADH1C polymorphism, as in our study, showed a small influence on the risk of alcoholism." (PMID 33551739, 2021). "A genome-wide association study also demonstrated an association between ADH1C rs2241894 and alcohol dependence in African and European Americans14." (PMID 32107439, 2020). "For instance, we were able to link S100A11 and SERPINC1, proteins associated with pQTLs in hotspots 17 and 18, to alcohol dependence through their distant pQTL variants located in ADH1C." (PMID 32778093, 2020). "The findings assessing this proposed mechanism of action—that ADH1B and ADH1C variations reduce alcohol dependence risk through elevated acetaldehyde levels, heightened responses to alcohol, and reduced drinking—have been inconsistent." (PMID 27163368, 2016). "Of the studies conducted, one study found that the ADH1B*1 and ADH1C*2 alleles were both associated with alcohol dependence in Mexican Americans." (PMID 25527893, 2014). "These SNPs, which define the frequently studied ADH1C *1/*2 haplotypes, have been reported to be associated with risk of alcohol dependence and with alcohol consumption." (PMID 23516558, 2013). "Our replication study provides further evidence that the minor allele of rs1614972 in the alcohol dehydrogenase 1C gene (ADH1C) is associated with decreased risk of alcohol dependence." (PMID 23516558, 2013). "In conclusion, data presented here provide additional support for the association of SNP rs1614972 in the ADH1C gene with alcohol dependence, as well as with alcohol consumption among alcoholics and non-alcoholics." (PMID 23516558, 2013). "The strongest evidence of association with alcohol dependence was obtained for SNP rs1614972 in the ADH1C gene (OR = 0.80, 95% CI = (0.70, 0.92), p = 0.0017)." (PMID 23516558, 2013). "Our analysis of 808 alcohol-dependent cases and 1,248 controls provided evidence of association of alcohol dependence with SNP rs1614972 in the ADH1C gene (unadjusted p = 0.0017)." (PMID 23516558, 2013). "ADH1C*1 also has been related to protection against alcohol dependence, but this association has been attributed to the ADH1C gene being in close proximity to the ADH1B gene on the chromosome so that the genotypes are correlated." (PMID 17718397, 2007). "Studies have demonstrated that a certain variant of the gene encoding ADH1B (ADH1B*3) is associated with a reduced risk of alcoholism in Afro-Trinidadians, as is a variant of the gene encoding ADH1C (i.e., ADH1C*1) in Indo-Trinidadians." (PMID 17718398, 2007). "Variants of three genes encoding alcohol-metabolizing enzymes, the aldehyde dehydrogenase gene ALDH2 and the alcohol dehydrogenase genes ADH1B and ADH1C, have been associated with reduced rates of alcohol dependence." (PMID 17718397, 2007). "In addition, unlike the FAS population, they also have the ADH1B*3 (rs2066702) and ADH1C*1 (rs1693482) polymorphisms, which cause a faster accumulation of acetaldehyde in the blood when they drink alcohol, protecting them from possible alcoholism in adulthood." (PMID 38886650, 2024). "Finally, ADH1C, encoding alcohol deshydrogenase 1C, is found to be associated with three addiction disorders: alcohol dependence, OUD and SUD." (PMID 37937232, 2023).
alcohol dependence (continued). "Our findings support the use of naltrexone in those patients who might be less susceptible to alcohol dependence (i.e., ADH1C*1 and ALDH2*2), wherein these polymorphisms have been also related to the AUD protection." (PMID 34680127, 2021). "Other variations in ADH and ALDH genes may also affect the risk of alcohol dependence and abuse, as ADH1C*1 and ADH1B*." (PMID 34680127, 2021). "ADH1C protein is involved in alcohol metabolism and associated with alcohol dependence." (PMID 32778093, 2020). "ADH1C has been shown to be associated with alcoholism in different populations." (PMID 32093702, 2020). "Some studies showed that ADH1C*1 and ADH1B*2 are in linkage disequilibrium, suggesting that associations of ADH1C*1 with alcohol dependence may be attributed to correlation with ADH1B*2." (PMID 27163368, 2016). "Meta-analysis of the association of alcohol dependence with ADH1C SNP rs1614972." (PMID 23516558, 2013). "It has been widely known that ADH1C*1 allele encode isozymes with higher catalytic activity than the one encoded by ADH1C*2 allele and result in more production of AA, which is a major part in ethanol-related carcinogenesis and alcoholism." (PMID 22675424, 2012). "Thus, additional studies should investigate the association of other ADH1C SNPs with alcohol dependence and related phenotypes, as well as the potential functional role of the rs1614972 SNP, and SNPs in LD with it including the non-synonymous SNPs rs1693482 and rs698." (PMID 23516558, 2013). "A variant of the ADH1C gene, the ADH1C*1 allele, also has been well studied with respect to alcohol dependence, but the results have been inconsistent because of limited sample sizes, ethnic variation, and the close proximity of the ADH1B and ADH1C genes." (PMID 27163368, 2016). "In particular, the ADH1B*2, ADH1B*3, ADH1C*1, and ALDH2*2 alleles have shown protective associations with alcohol dependence." (PMID 27163368, 2016). "Certain genetic variants (i.e., alleles)—particularly the ADH1B*2, ADH1B*3, ADH1C*1, and ALDH2*2 alleles—have been associated with lower rates of alcohol dependence." (PMID 27163368, 2016). "First, the presence of ADH1C*1 in Indo-Trinidadians and ADH1B*3 in Afro-Trinidadians is associated with reduced risk for alcoholism." (PMID 17718398, 2007). "ADH1C*2 has protective effects on liver cirrhosis and alcohol chronic pancreatitis, an is also associated with a lower rate in alcohol dependence among Asian population, maybe because ADH1B and ADH1C are in linkage disequilibrium." (PMID 19506733, 2008). "For example, certain ADH1B and ADH1C alleles encode particularly active ADH enzymes, resulting in more rapid conversion of alcohol (i.e., ethanol) to acetaldehyde; these alleles have a protective effect on the risk of alcoholism." (PMID 17718394, 2007). "Importantly, all traits that showed significant sex-dependent colocalization with ADH1C eQTLs were related to alcohol drinking frequency, but not alcoholism." (PMID 36635277, 2023). "The ADH1C*1 allele also appears to have protective effects against alcoholism in Asian populations; however, this protection can be attributed to the fact that this allele usually is co-inherited with the protective ADH1B*2 allele and is not an independent effect of the ADH1C*1 allele." (PMID 17718394, 2007).
breast carcinoma (10 papers, 2012 to 2024). "Earlier genetic studies found that rs1229984 in ADH1B and rs698 in ADH1C modify the alcohol association with breast cancer, particularly in pre-menopausal women." (PMID 37308906, 2023). "It was demonstrated that the ADH1C*1 allele plays a crucial role in breast cancer risk in premenopausal women." (PMID 36310188, 2023). "In a meta-analysis of a total of 6,159 cases and 5,732 controls in Caucasians, the pooled OR with 95% CI for breast cancer risk connected with ADH1C genotype was evaluated." (PMID 36310188, 2023). "Premenopausal women carrying ADH1C*1 variant are found to be at a 1.8 times greater risk for breast cancer than women with other two genotypes." (PMID 28805741, 2017). "In addition, premenopausal women who were homozygous for ADH1C*1 and consumed higher amounts of alcohol had a greater risk of breast cancer than women whose alcohol consumption was moderate (odds ratio, OR = 3.6; 95% CI 1.5–8.8)." (PMID 36310188, 2023). "Cancer subtype based on our ANOVA results was significantly associated with the expression of all but 2 (ADH1C and ERCC2) alcohol-breast cancer risk related genes." (PMID 32078659, 2020). "The TNBC-specific methylation and mRNA expression patterns of the ATP1A1, ADH1C, and CFH genes were also significantly altered in the TCGA cohort, depending on the breast cancer subtype." (PMID 38730618, 2024). "For example, ZCRB1 was overexpressed in lymphoma, and ADH1C in cervical cancer and esophageal cancer, and YTHDC2 in breast cancer, gastric cancer, head and neck cancer, myeloma, and sarcoma." (PMID 34178026, 2021). "Several other large studies, however, indicate that SNPs in ADH1B, ADH1C, and CYP2E1 do not modify associations of alcohol intake with breast cancer risk." (PMID 37308906, 2023). "A randomized phase III trial found that another SNP rs1693482 in ADH1C significantly affected OS in breast cancer patients undergoing neoadjuvant chemotherapy and without the need to achieve PCR." (PMID 36212135, 2022).
gastric cancer (9 papers, 2017 to 2025). A primary or metastatic malignant neoplasm involving the stomach. "The association of ADH1C (rs698) polymorphism with gastric cancers is inconsistent across the studies." (PMID 39063094, 2024). "Studies have shown that ADH1C polymorphisms were associated with various cancer risks such as gastric cancer and oral squamous cell carcinoma." (PMID 35236335, 2022). "Genetic polymorphism of the ADH1C gene (ADH1C*1 allele) is associated with various human cancers, such as gastric cancer, oral cancer and CRC, for it encodes an alcohol dehydrogenase producing 2.5 times more acetaldehyde." (PMID 35300114, 2022). "However, compared with ADH1C*1/*1 carriers who drink 0 to <150 g/week of ethanol, ADH1C*2 allele carriers who drink ≥150 g/week of ethanol demonstrated an increased risk of gastric cancers (OR, 2.54; 95% CI, 1.05–6.17)." (PMID 39063094, 2024). "However, ADH1C G allele carriers who drink ≥150 g/week of ethanol had a 2.5-fold increased risk of gastric cancer development (OR = 2.54, 95% CI = 1.05−6.17) relative to AA genotype carriers who do not drink at all or drink <150 g/week (P for interaction = 0.02)." (PMID 28538665, 2017). "ADH1C is involved in tumor immune cell infiltration, and ADH1B is associated with increased risk of breast and gastric cancer." (PMID 41374967, 2025). "Genetic polymorphisms of ADH1B, ADH1C and ALDH2 have been reported involving in the development and progression of many cancers, such as gastric cancer, head and neck cancers, esophageal cancer, and pancreatic cancer." (PMID 35280985, 2022). "No studies have investigated the association of ADH1C or CYP2E1 polymorphisms with multiple gastric cancers." (PMID 39063094, 2024). "Studies have shown CLCA1 downregulation in CRC and ADH1C downregulation in gastric cancer." (PMID 31211760, 2019).
colorectal cancer (8 papers, 2018 to 2025). A primary or metastatic malignant neoplasm that affects the colon or rectum. "Another study stated that decreased expression of ADH1C from adenoma to early and advanced stages of colorectal carcinomas was associated with reduced all-trans retinoic acid biosynthesis." (PMID 41465541, 2025). "In colorectal cancer, ADH1C is reported to inhibit progression through the serine metabolic pathway, and is a protective factor for CRC patients via bioinformatics analysis." (PMID 36671526, 2023). "It has also been concluded that with the continuous reduction of ADH1C expression levels, the prognosis of colorectal cancer patients can gradually worsen." (PMID 36212135, 2022). "Accordingly, previous studies have commonly focused on ADH1B, ADH1C, ALDH2, CYP2E1, and MTHFR genotypes as modifiers of the association between alcohol consumption and risk of alcohol-related cancers, including colorectal cancer." (PMID 29464080, 2018). "In colorectal cancer, ADH1C acts as a tumor suppressor gene." (PMID 38685045, 2024). "ADH1B, ADH1C, RDHL, and RDH5 mRNAs were decreased in colorectal cancer samples, and expression of ADH1B and ADH1C mRNAs decreased regarding progression from adenoma to early and more advanced colorectal cancer." (PMID 37569466, 2023). "FABP6, hypermethylated SFRP1, XDH, PLAU, ADH1C, HSD17B2, and SPP1 have been identified more as a colorectal cancer biomarker than as a therapeutic target at present." (PMID 34381520, 2021). "Significant downregulation of ADH1B, ADH1C, and RDHL mRNAs was seen for colorectal cancer samples." (PMID 37569466, 2023).
liver cancer (7 papers, 2017 to 2025). An epithelial or non-epithelial malignant neoplasm that arises from the liver. "ADH1C is associated with a poor prognosis for liver cancer and lung adenocarcinoma." (PMID 38685045, 2024). "Some studies found that the expression of ADH1C was significantly downregulated in hepatocellular carcinoma tumor samples compared with normal liver samples and whose high expression of ADH1C was significantly associated with a good survival rate in liver cancer patients." (PMID 36212135, 2022). "IN HPA database, immunohistochemistry showed that the expressions of APEX1, ME1, S100A10 and ACACA in liver cancer tissues were significantly higher than those in paired normal liver tissues, while ADH1C, and CYP2C9 were expressed at low levels in tumor tissues compared with adjacent normal tissues." (PMID 36456877, 2022).
lung carcinoma (7 papers, 2017 to 2024). "Some analyses found that ADH1C plays a vital role in developing breast, liver, colorectal, and lung cancers." (PMID 36212135, 2022). "Glutathione S-Transferase Omega 1 (GSTO1), Sulfotransferase Family 2B Member 1 (SULT2B1), ADH1A, ADH1B, and ADH1C were downregulated in lung cancer versus normal tissue, while ALDH3A2 and MTHFD2 were upregulated in lung cancer tissue versus normal adjacent tissue." (PMID 31717324, 2019). "Polymorphisms of ADH1C are associated with the risk of upper aerodigestive tract cancer, while ALDH1A1 expression has been found to be down-regulated in various types of lung cancer." (PMID 27738743, 2017). "For lung cancer patients, high expression of ADH1B, ADH1C, ADH4, and ADH5 genes can achieve a better prognosis." (PMID 36212135, 2022).
adenoma (5 papers, 2019 to 2025). A neoplasm arising from the epithelium. "In cancer-adenoma, we found downregulation of ADH1C, which again implicates decreased ATRA production in the progression of duodenal neoplasia in FAP." (PMID 31211760, 2019). "In addition, the latest study showed that ADH1C is down-regulated in familial adenomatous polyposis case adenomas, but up-regulated in patients with ulcerative colitis." (PMID 35300114, 2022). "For the adenoma–adenoma comparison made in the reference article, the CLCA1 and ADH1C genes were downregulated." (PMID 37565794, 2023). "In the adenoma-adenoma comparison, downregulation of several DEGs (CLCA1, ADH1C, ANXA10) in FAP case adenomas was observed." (PMID 31211760, 2019). "In this study, CLCA1 and ADH1C are downregulated in cancer compared to adenoma and in adenoma from FAP cases compared to FAP controls, indicating that downregulation of these DEGs within adenomas may indicate increased likelihood of neoplastic progression." (PMID 31211760, 2019). "Likewise, considering the variable importance values obtained, LOC399753, APOA4, MIR548X, and ADH1C genes can be used to differentiate duodenal cancer patients with FAP from the adenoma tissues of non-cancer patients with only FAP for adenoma–adenoma comparison." (PMID 37565794, 2023).
alcohol use disorder (5 papers, 2013 to 2025). "Genes such as ADH1B and ALDH2 have been shown to be protective in Asian populations, while ADH1C has been shown to increase the risk for alcohol use disorder." (PMID 38359015, 2024). "The ALDH2*1 allele was found as a risk factor for alcohol abuse and alcohol cirrhosis, and combined genotypes of ADH1B rs1229984, ADH1C rs698 and ALDH2 rs671 with non‐acetaldehyde accumulation increase alcohol cirrhosis risk." (PMID 40730494, 2025). "Many HCC patients were inferred to have a background of alcohol abuse; thus, ADH1C overexpression can enhance the ability to transform alcohol into acetaldehyde rapidly and indirectly protects liver function from damage due to alcohol and forming HCC." (PMID 32903581, 2020). "Further studies of the role of ADH1C in alcohol use disorders should consider other alcohol-use related phenotypes." (PMID 23516558, 2013).
alcoholic liver diseases (4 papers, 2024). A disorder caused by damage to the liver parenchyma due to alcohol consumption. "Among the top 30 genes in the gene regulatory network, 7 genes are enriched in alcoholic liver disease (hsa04936), including TNF, IL6, IFNA1, CYP2E1, ALDH2, ADH1B, ADH1C." (PMID 38429802, 2024).